EGFR (epidermal growth factor receptor)
Diseases named in the same sentence as EGFR in open-access papers (continued):
Sharing a sentence is not in itself a finding about the gene and the disease.
lung cancer (continued). "In a gefitinib-sensitive lung cancer cell line HCC827, focal amplification of MET was found to stimulate ErbB3 phosphorylation which in turn activated downstream PI3K/Akt signaling axis compensating the inhibitory effect of gefitinib on EGFR." (PMID 29455669, 2018). "Epidermal growth factor receptor (EGFR) is a transmembrane glycoprotein which could regulate cellular proliferation and its expression reflects the progress of lung cancer." (PMID 30250814, 2018). "Combined the targeting of EGFR and PKC may have an additive or synergistic effects in lung cancer treatment." (PMID 28399187, 2017). "In contrast to other driver oncogenes in lung cancer, such as EGFR and ALK, molecularly targeted drugs to KRAS have not yet been developed and therapeutic targeting of KRAS-mutated lung adenocarcinoma remains a huge challenge." (PMID 28380052, 2017). "To test the hypothesis, we used YM155 to reduce tumorsphere formation derived from EGFR-positive lung cancer cells, because YM155 was demonstrated to suppress EGFR in pancreatic cells by degrading it." (PMID 28787001, 2017). "Our analysis of electronic health records of lung cancer patients who received proteomic testing at the VA revealed that EGFR testing was significantly underutilized or not properly documented." (PMID 28558785, 2017). "Three phosphorylation sites (Y1110, Y1172, and Y1197) connected to erlotinib sensitivity were validated using IP-SRM in lung cancer tissue samples; Y1197 phosphorylated peptides showed good signal, which confirmed that IP-SRM strategy is suitable for EGFR phosphorylation measurement." (PMID 28265552, 2017). "Because previous studies have observed a relationship between PD-L1 expression and EGFR activation in lung cancers (but no data regarding EGFR-TKI resistance and PD-L1 expression), we compared EGFR phosphorylation status between these cells." (PMID 29119113, 2017). "Lastly, two clinical trials using TLR9 agonists (IMO-2055, phase II; MGN1703, phase I) have been utilized as immunomodulators for lung cancer and found possible anti-tumor efficacy, either in combination with erlotinib (EGFR inhibitor) and bevacizumab (VEGFA inhibitor) or alone (MGN1703)." (PMID 29190881, 2017). "Here, we show higher levels of epidermal growth factor receptor (EGFR), but lower levels of miR-370 expression in most human lung cancer cells and non-tumor cells." (PMID 29152147, 2017). "We also examined the expression of G9A in lung cancer using the oncomine database, and found that G9A is upregulated in LUAD regardless of EGFR or KRAS mutation status." (PMID 28383547, 2017). "The HER family is composed of four members, including EGFR/HER1/ErbB1, HER2/ErbB2, HER3/ErbB3, and HER4/ErbB4, and plays a key role in the pathogenesis of various human solid tumors, including breast, gastric and lung cancers." (PMID 29233126, 2017). "The relationship between EGFR-RAS activity and YAP/TAZ activity in lung cancer has been examined, but nonetheless there remain substantial gaps in our understanding of the relationship between them during lung cancer progression." (PMID 29340023, 2017). "To explore the relevance of the sensitivity/resistance profiles derived from stably transduced Ba/F3 cells, we also performed MTS assays in human lung cancer-derived cell lines in the presence and absence of EGFR-TKIs." (PMID 29285266, 2017). "To elucidate and investigate the possible mechanism of the stemness property in EGFR-positive lung cancer, we used YM155, a stemness inhibitor, and investigated its cellular mechanism and potential as an inhibitor of cancer stemness in EGFR-derived cancer stemness models." (PMID 28787001, 2017). "In this study, we found that MET/EGFR and their downstream signaling ERK1/2 and AKT may be the targets of FAM83H-AS1 in lung cancer, indicating that FAM83H-AS1 may be a potential therapeutic target." (PMID 28198463, 2017).
lung cancer (continued). "Use of EGFR-TKIs was not different between patients with or without family history of lung cancer (χ2 p = 0.446)." (PMID 28486527, 2017). "However, CDCP1 levels and EGFR signaling, as indicated by phospho-EGFR expression, were dampened in ADAM9-knockdown lung cancer cells, and ADAM9-knockdown cells showed more sensitivity to EGFR inhibitor treatment (Tarceva) than control cells (shGFP)." (PMID 28537886, 2017). "This mutation has been reported twice in lung cancer (COSMIC databank, accessed 31.10.16) and is activating from a biological point of view but does not confer sensitivity to EGFR-TKIs." (PMID 29100434, 2017). "From January 1, 1997 to December 31, 2012, a total of 1,707 statin and 6,828 non-statin matched lung cancer cohorts with EGFR-TKIs treatment were studied." (PMID 28158206, 2017). "To confirm the superior activity of brigatinib against the triple-mutant EGFR, we performed in vivo experiments by administering brigatinib or osimertinib to nude mice into which EGFR-triple-del19 expressing PC9 lung cancer (PC9-triple mutant) cells had been subcutaneously injected." (PMID 28287083, 2017). "Finding that EGFR signaling triggers an increase in YAP1 protein expression and its activity, we next focused on understanding the biological roles of YAP1 in EGFR-dependent lung cancer cells." (PMID 29163769, 2017). "It has been reported that EGFR and SCD1 play significant roles in lung cancer." (PMID 28724430, 2017). "Our findings also suggested that the inhibitory effects of AC-93253 iodide on lung cancer progression may be attributable to its ability to modulate multiple proteins, including Src, PI3K, JNK, Paxillin, p130cas, MEK, ERK, and EGFR." (PMID 29132432, 2017). "Additionally, M2-like TAMs secrete EGF-like ligands to activate EGFR pathway in lung cancer cells, which ultimately promoting EMT that can be inhibited by a cannabinoid receptor 2 (CB2) agonist JWH-015 via downregulation of EGFR signaling." (PMID 28467800, 2017). "Their results demonstrated that the co-delivery nanoparticles could overcome EGFR-TKI resistance and held strong potential for effective management of EGFR-mutant lung cancer." (PMID 29191057, 2017). "For example, increasing cell density in HCT116, CNE-2Z and A549 lung cancer cells increased the expression and phosphorylation of EGFR, but not in HSAEC2-KT normal lung cells." (PMID 28061454, 2017). "Simvastatin plus gefitinib improved the response rate and PFS in patients with EGFR wild-type non-adenocarcinoma lung cancer." (PMID 28158206, 2017). "The results obtained suggest that MET and EGFR inhibitor-based therapies can be investigated using a preclinical platform, which accurately mimics the clinical situation of lung cancer patients without RTK/RAS/RAF oncogene alterations." (PMID 28806950, 2017). "Not surprisingly, multiple components in the EGFR-Akt-mTOR pathway were highly expressed/activated in the A549 lung cancer cells but not in HSAEC-2KT normal lung cells, which is consistent with their oncogenetic functions." (PMID 28061454, 2017). "Why are mutation rates in epidermal growth factor receptor (EGFR) and erb-b2 receptor tyrosine kinase 2 (ERBB2) higher in lung cancer from never smokers than that from smokers?" (PMID 28974261, 2017). "In this study, we extensively studied the molecular mechanism of ENb-TRAIL mediated cell killing in a broad spectrum of colorectal cancer, lung cancer, and glioma cell lines non-responsive to EGFR and death receptor targeted therapies." (PMID 28572590, 2017). "We demonstrate in our new in-vitro data that upon EGFR activation LysRS is released from the MSC in NSCLC, phosphorylated at position serine 207 in a MAPK-ERK1/2 dependent manner and translocates to the nucleus in lung cancer cells." (PMID 29029422, 2017). "A bio-distribution study using EGFR-targeted chitosan nanoparticles showed six-fold higher tumor targeting efficiency than non-targeted nanoparticles in lung cancer tumor models." (PMID 28290155, 2017).
lung cancer (continued). "Previous studies have shown that HDAC6 knockdown inhibits EGFR expression in A549 lung cancer cell line, without affecting their growth." (PMID 29113288, 2017). "As the implications of P-s207 LysRS in human cancers have not been established, we focused our initial studies on lung cancer due to the importance of the EGFR in the prognosis and treatment of this cancer group." (PMID 29029422, 2017). "We found that these proteins were not changed after LINC00152 siRNA treatment at 72 hours indicating that EGFR signaling was not involved in LINC00152 regulation in these lung cancer cells." (PMID 28592840, 2017). "Further studies are warranted to elucidate the clinical and/or biological significance of uncommon mutations, doublet non-p.L858R missense mutations of EGFR, and concomitant kinase-impaired BRAF mutations in lung cancers." (PMID 29228562, 2017). "It has been reported that the VEGF/VEGFR-2 feed-forward loop increases VEGF secretion in lung cancer via mTOR-dependent regulation that is required for the activation of downstream signaling, and the over-expression of VEGFR-1 reduces EGFR-TKIs sensitivity in different human cancer cells." (PMID 28288164, 2017). "Finally, the third study to complete was the lung cancer trial (NCT00994123), in which patients with EGFR wild-type NSCLC were randomized 2:1 to receive seribantumab in combination with erlotinib at a dose of 100 mg/day, or erlotinib alone at 150 mg/day." (PMID 28725482, 2017). "We examined different densities of A549 lung cancer cells and HSAEC2-KT normal lung cells side-by-side to see whether the EGFR-Akt-mTOR pathway is differentially regulated by cell type and cell density." (PMID 28061454, 2017). "We hope to emphasize the possibility that EGFR-TKIs and/or suppressing PMPA could be effective for the PDPN-positive lung cancers and bladder carcinomas." (PMID 28642617, 2017). "While L747 in frame deletion mutants are common in lung cancer and are sensitive to EGFR TKIs, the L747* in MSI-H would not be expected to activate the kinase and is predicted to be insensitive to TKIs." (PMID 28591715, 2017). "The biologic dissimilarity of lung cancer in never-smokers versus ever-smokers are shown in differential response according to specific therapies including EGFR inhibitors, and in distribution of histology such as adenocarcinoma in never-smokers." (PMID 26985396, 2016). "Although several reports have identified SerpinB2 as an important marker for lung cancer progression and metastasis, the relationship between SerpinB2 and EGFR-TKI resistance has not been clearly elucidated." (PMID 27558531, 2016). "Notch and epidermal growth factor receptor (EGFR) signaling are essential in cell proliferation, differentiation, and apoptosis, and thereby may contribute to the development of lung cancer." (PMID 27770511, 2016). "Recently, lung cancer in female gender and never smokers has received considerable attention with the advent of EGFR TKI treatment." (PMID 26979333, 2016). "To dissect the signaling downstream of TOPK responsible for cancer cell survival and division, we assessed the activation of potential TOPK substrate proteins, including ERK, JNK and c-Jun in EGFR-TKI-resistant (A549 cells) and -responsive (H358 cells) lung cancer cells." (PMID 26745678, 2016). "The results showed we were able to accurately pinpoint the presence or absence of T790M, a common resistance mechanism in EGFR mutant lung cancer in the model PC9 cell line." (PMID 26924553, 2016). "H441 lung cancer cells were pretreated with or without EGFR inhibitor in the presence of MART-1 (M27) peptide or CMV pp65 protein-derived control peptide, and used as target cells for Mart-1/HLA-A2 specific CTL in standard CTL assay." (PMID 27467256, 2016).
lung cancer (continued). "Furthermore, MIIP-promoted downregulation of EGFR inhibits downstream activation of Ras and blocks the MEK signal transduction pathway, resulting in inhibition of lung cancer cell proliferation." (PMID 26824318, 2016). "Indeed, the expression level of PTPN13 was much lower in EGFR-TKIs resistant lung cancer cell lines than BEAS-2B cells, however EGFR-TKIs sensitive cells have relatively high expression levels of PTPN13." (PMID 27285768, 2016). "Accumulation of EGFR and KRAS genetic alterations leads to the pathogenesis of lung cancer." (PMID 27863408, 2016). "Our preclinical evidence suggest therapeutic potential of AZD9291 on EGFR-mutant lung cancer patients with CNS metastasis including LMC with or without resistance to other EGFR-TKIs." (PMID 26716903, 2016). "At the time of initiation of the current phase II study no prospective data were available about the efficacy of EGFR TKI in EGFR mutant lung cancers." (PMID 27032107, 2016). "One of the possible reasons is greater sensitivity of lung cancer to treatment with EGFR tyrosine kinase inhibitors in Asian patients than in non-Asian patients." (PMID 27244238, 2016). "No other examined mutations (EGFR, HER2, HER4, KRAS or BRAF) were found in the lung tumor specimen of the patient, suggesting that HER3-V855Ais the primary driver for the lung cancer pathogenesis." (PMID 26689995, 2016). "Based on our preclinical evidence, we posit that clinical trials are required to evaluate the efficacy of AZD9291 treatment in EGFR-mutant lung cancer patients with CNS metastasis including LMC with or without resistance to other EGFR-TKIs." (PMID 26716903, 2016). "To understand changes in the levels of miRNAs in response to therapy for the same individuals, we recruited a small cohort of late-stage lung cancer patients who were assigned to receive EGFR TKI, and in some cases that progressed on EGFR TKI, with subsequent follow-up radiotherapy or chemotherapy." (PMID 27325363, 2016). "Therefore, to explore the molecular mechanism by which HGF reduces sensitivity to gefitinib in lung cancer harboring wild-type EGFR, we examined the phosphorylation status of MET, EGFR, ErbB3, and the downstream signaling pathways by western blotting." (PMID 26919104, 2016). "EGFR-tyrosine kinase inhibitors (EGFR-TKIs) such as first generation gefitinib/erlotinib and second generation afatinib showed remarkable activity in EGFR-mutant lung cancer patients with or without CNS metastasis." (PMID 26716903, 2016). "We have evaluated SALL4 expression in lung cancer in large cohorts of patients, and observed that SALL4 expression is upregulated in a subset (about 16%) of these patients including EGFR mutation negative cases." (PMID 27705911, 2016). "This may be the result of heterogeneity or variation in p-MET or the activation of compensatory pathways (e.g., EGFR, KRAS) in lung cancer." (PMID 27013592, 2016). "In addition, miR-143 is also chemosensitizer to docetaxel in prostate cancer by targeting KRAS and subsequently targeting EGFR/RAS/MAPK pathway, while miR-145 inhibits EGFR mutant lung cancer cell growth, sensitizing to gifitinib." (PMID 26824186, 2016). "This innovative nano-medicine can specifically target lung cancer cells with high EGFR expression rather than those with low EGFR level." (PMID 27151505, 2016). "However, EGFR and ALK aberrations collectively account for only approximately 15% of all NSCLCs in the US, and the overall survival rate for lung cancer patients remains extremely poor (5-year survival rate of ~15%)." (PMID 27705911, 2016). "Recently, non-tobacco-using-patients with lung cancers have received considerable attention with the application of EGFR TKIs." (PMID 26739511, 2016). "First-generation EGFR TKI exposure did not influence the prevalence of T790M in lung cancer acquired resistance to afatinib." (PMID 26862733, 2016).
lung cancer (continued). "Based on the findings of this study, lung cancers with wild-type EGFR are not addicted to EGFR signal, in contrast to EGFR mutant cells." (PMID 26919104, 2016). "Remarkably rapid and often profound responses to EGFR TKIs, such as gefitinib or erlotinib, are frequently observed in a portion of lung cancer patients, in particular, non-smoker Asian females with pulmonary adenocarcinoma." (PMID 26654941, 2016). "Besides, curcumin inhibited the enzymatic activity of the epidermal growth factor receptor (EGFR) intracellular domain, and also influenced the cell membrane environment of EGFR, which was involved in the growth of lung cancer." (PMID 27529277, 2016). "Finally, because IL10 deprivation abolishes lung cancer formation by inhibiting the formation of the microenvironment and the expression of EGFR, the future development of anti-IL10 compound(s) will be of benefit to lung cancer therapy." (PMID 26956044, 2016). "We previously showed, in several lung cancer cell lines, that AvidinOX-anchored bCet induces a dramatic decrease of total and activated EGFR in both nuclear and non-nuclear cell compartments." (PMID 26575422, 2016). "In addition, EGF stimulation resulted in simultaneous TOPK and c-Jun phosphorylation, both in HEK293 cells and H358 cells that expressed ectopic TOPK and in EGFR-TKI-resistant A549 and H1975 lung cancer cells that expressed high endogenous TOPK." (PMID 26745678, 2016). "In our current work, we found that the hyperthermic conditions used in clinical practice for treating lung cancer patients by IPHC does not significantly affect the EGFR protein level in lung cancer cell lines." (PMID 26654941, 2016). "We recently reported that AvidinOX-anchored bCet inhibits dimerization and signalling, blocks endocytosis, induces massive lysosomal degradation and abrogates nuclear translocation of EGFR, in lung cancer cells at doses otherwise not effective." (PMID 26575422, 2016). "So far, most reports on re-biopsy procedures after EGFR-TKI resistance have been on computed tomography-guided transthoracic needle biopsy (CTNB), which is also the common first method of choice for the initial diagnosis of lung cancer." (PMID 27457475, 2016). "Taken together, the results of this study highlight an important role for miR-218-5p in the regulation of EGFR in NSCLC and may open new avenues for future lung cancer therapies." (PMID 27057632, 2016). "Application of EGFR inhibitors, such as erlotinib and gefitinib, is a routine therapeutic targeting strategy for lung cancer patients with mutant EGFR, but not for those with wild-type EGFR." (PMID 26958807, 2016). "Our above results showed the gefitinib and PA-MSHA could suppress EGFR-mediated p-AKT and p-ERK pathway in three lung cancer cell lines, including A549." (PMID 27283902, 2016). "Epidermal growth factor receptor (EGFR)-targeting antibodies or small molecular EGFR inhibitors are widely used to treat patients with gastrointestinal (GI), breast, head and neck, and lung cancers." (PMID 26380220, 2015). "As a consequence, the abundance of OCT-4 and EGFR, two validated targets of miR-145-5p, was increased in primary lung cancer and their matched-brain metastasis compared to non-tumoral tissues." (PMID 26440147, 2015). "This case points out the histologic “flexibility” of EGFR mutant lung cancers and the importance for appropriate molecular testing in nonsmokers with lung cancer of any histologic type." (PMID 26366316, 2015). "Moreover, in lung cancer, reduced MCL1 expression sensitized epidermal growth factor receptor mutant non-small cell lung cancers to MEK inhibitors." (PMID 26636651, 2015). "Our model suggests that in a group of mutant KRAS lung cancers, EGFR is not the major upstream signaling activator, but that this role is also played by HER2 and HER3." (PMID 25992771, 2015).